BCL2 (BCL2 apoptosis regulator)
Diseases named in the same sentence as BCL2 in open-access papers (continued):
Sharing a sentence is not in itself a finding about the gene and the disease.
neuroblastoma (continued). "RNAseq analysis revealed high expression of BCL2L1 in MBG3 and BCL2 in neuroblastomas." (PMID 38942989, 2024). "Here, we asked whether BH3-mimetics inhibiting BCL2 proteins may eliminate chemoresistant neuroblastoma cells." (PMID 37723317, 2023). "Moreover, combination therapy with antimitotic compounds and BCL2 inhibitors exploited mitotic stress induced by antimitotics and was synergistically toxic to neuroblastoma cell lines." (PMID 37958555, 2023). "Yet, our in vitro results suggest that the MCL-1 inhibitor S68345 could also be effective in a subset of neuroblastoma tumors with lower BCL-2 levels, where BIM is bound to MCL-1." (PMID 36895472, 2023). "While a prominent role of MCL1 in chemoresistant cancer has been described in multiple studies, the loss of sensitivity to BCL2/BCL-XL inhibitors observed here may be more controversial and potentially limited to neuroblastoma." (PMID 37723317, 2023). "In addition, vanillin was shown to exhibit neuroprotective effects by regulating inflammatory cytokines and BAX/BCl-2 in rotenone-induced SH-SY5Y neuroblastoma cells." (PMID 37762386, 2023). "Collectively, these studies identified a significant role for BCL-2 in mediating neuroblastoma resistance apoptosis, which could be overcome by utilising combinational treatment strategies." (PMID 35568716, 2022). "Indeed, fewer viable cells were collected upon hypoxia, coinciding with the downregulation of the Bcl2-antiapoptotic protein, shown to be regulated by this miRNA in neuroblastoma or in the spermatocyte cell line." (PMID 35625614, 2022). "Indeed, preclinical studies using Bcl-2-specific inhibitors have demonstrated anti-tumor activity in neuroblastoma tumors with high Bcl-2 levels." (PMID 35884854, 2022). "Furthermore, recent research demonstrated that dual inhibition of BCL-XL and MCL-1 synergistically reduces viability and induces death in neuroblastoma cell lines displaying treatment resistance to individual BCL-2, BCL-XL, or MCL-1 inhibitors." (PMID 35568716, 2022). "In addition, there is only one study showing a direct binding of CNA to Bcl-2 in human neuroblastoma cells." (PMID 34573382, 2021). "Moreover, in Neuro-2a neuroblastoma cells, miR-210 exacerbates the hypoxia-induced apoptotic cell death through the directly targeting the Bcl-2 3′UTR." (PMID 35052722, 2021). "In this study, rh-omentin treatment could significantly reduce H/R-induced injury by inhibiting neuroblastoma apoptosis, as evidenced by remarkably decreased the cell apoptotic rate, Bax expression and increased Bcl2 expression." (PMID 35141232, 2021). "However, a single amino acid change in the SINV E2 from Q55 to H55 conferred both neurovirulence in mouse neuroblastoma (N18) cells and the ability to kill AT-3 cells expressing bcl-2, likely due to the alteration of the interaction between E2 and bcl-2." (PMID 34063663, 2021). "Besides, a neuroblastoma cell line co-transfected with Swedish mutant APP showed a higher Bax/Bcl2 ratio." (PMID 33276671, 2020). "Next, we investigated the expression of BCL-2 proteins in neuroblastoma cell lines." (PMID 32203216, 2020). "All tested BH3-mimetics were able to induce apoptosis in neuroblastoma cell lines, indicating that not only BCL-2 but also BCL-XL and MCL-1 may be promising therapeutic targets." (PMID 32203216, 2020). "Western blot analysis revealed that BCL-2 expression was very heterogeneous in neuroblastoma cell lines, with some cell lines displaying relatively high BCL-2 protein levels (SJNB-12, Lan-5 and SMS-KCNR), and others having relatively low expression (SH-EP, CHP-212)." (PMID 32203216, 2020). "Neuroblastoma cells display elevated expression of the antiapoptotic BCL-2 proteins, suggesting that BH3-mimetics may be a promising treatment option." (PMID 32203216, 2020). "Therefore, there is ongoing research to identify an inhibitor of Bcl-2 and Mcl-1 in N-Myc amplified neuroblastomas." (PMID 30885150, 2019).
neuroblastoma (continued). "Therefore, combined Bcl-2/Mcl-1 inhibition should be further elucidated as a treatment option in neuroblastoma with N-Myc amplification." (PMID 30885150, 2019). "Therefore, we evaluated the effect of TW-37, which inhibits Mcl-1 and Bcl-2 with almost the same affinity and which has also low affinity to Bcl-xL in neuroblastoma cell lines." (PMID 30885150, 2019). "Therefore, BH antagonism has become a treatment approach in neuroblastoma, and several agents have been developed with different selectivity to inhibit Bcl-2 and Mcl-1." (PMID 30885150, 2019). "Increased expression of Bcl-2 by statins has also been reported in SH-SY5Y neuroblastoma cells." (PMID 31319483, 2019). "2ME2 treatment inhibits Bcl-2 expression, while increasing Bax levels in human neuroblastoma cells." (PMID 30249026, 2018). "Another study confirmed that miR-204 binds to BCL2 mRNA in a neuroblastoma cell line and showed that it may also bind to NTRK2 (neurotrophic receptor tyrosine kinase 2)." (PMID 29382303, 2018). "On the contrary, a follow up high-throughput screen of venetoclax in ∼800 solid tumor cancer cell lines demonstrated that only two groups of solid tumor cancers were sensitive: a subset of MYCN-amplified neuroblastomas, and a subset of high BCL-2 expressing SCLCs." (PMID 30234143, 2018). "Besides, the ratio of Bcl-2 to Bax and the expression of caspase-3 were both changed in high glucose-cultured neuroblastoma cells." (PMID 29892266, 2018). "As the majority of neuroblastoma tumors is dependent on high BCL2 expression levels for survival, we evaluated the effects of combined venetoclax/idasanutlin treatment on cell viability and apoptosis in neuroblastoma cell lines with high BCL2 expression levels." (PMID 28915653, 2017). "We observed that neuroblastoma cells express either BCL2, MCL1 or both." (PMID 28915653, 2017). "However, CS pretreatment significantly attenuated 6-hydroxydopamine-induced apoptotic signals, including imbalance of the Bcl-2/Bax ratio, release of cytochrome c, and activation of caspase-9 and caspase-3 in a human neuroblastoma cell line." (PMID 28617322, 2017). "Our findings suggest that neuroblastoma patients with high BCL-2 and BIM/BCL-2 complex levels might benefit from combination treatment with ABT199 and compounds that inhibit MCL-1 expression." (PMID 27056887, 2016). "In line with previous results obtained with ABT263, neuroblastoma cell lines expressing high BCL-2 mRNA levels responded more potently to ABT199 than low BCL-2-expressing cell lines, with an over 90-fold difference in average LC50 value (i.e., 0.17 μM versus 15.46 μM, respectively)." (PMID 27056887, 2016). "A large subset of neuroblastoma patients have enhanced levels of the anti-apoptotic gene BCL-2." (PMID 27056887, 2016). "We demonstrate that the presence of MYCN amplification in neuroblastoma exhibits synthetic lethality when treated with the BCL-2 targeting agent ABT-199, and that these tumors are further sensitized by the addition of the Aurora A inhibitor, MLN8237, in cell culture models and diverse mouse models." (PMID 26859456, 2016). "PARP cleavage induction in the high BCL-2-expressing cell lines was already observed after treatment with only 7.5 nmol/L ABT199, while for the low BCL-2-expressing neuroblastoma cell lines PARP cleavage was only detected in SKNAS after treatment with 10 μmol/L ABT199." (PMID 27056887, 2016). "Taken together, the results presented in this study strongly suggest that children with neuroblastoma tumors expressing high levels of BCL-2 and the BIM/BCL-2 complex might benefit from combined treatment with ABT199 and compounds that inhibit MCL-1." (PMID 27056887, 2016).
neuroblastoma (continued). "Analysis of drug-sensitivity data of ∼500 solid tumor cancer cell lines from a high-throughput drug screen indicated that among all solid tumor types, neuroblastoma cell lines were exquisitely sensitive to the in-clinic BCL-2/BCL-2/xL inhibitor ABT-263 (navitoclax)." (PMID 26859456, 2016). "In addition, overexpression of BCL-2 in the low BCL-2-expressing neuroblastoma cell line SY5Y resulted in a strong increase in sensitivity to SY5Y." (PMID 27056887, 2016). "Similarly, the anti-apoptotic effects of CT has been shown previously with conserving mitochondrial membrane potential, reducing Bax/Bcl-2 ratio and inhibiting cytochrome c release in nitric oxide induced neuroblastoma cells apoptosis." (PMID 23341883, 2013). "BCL2 levels are high in the majority of neuroblastoma tumors." (PMID 24348903, 2013). "Recently, BCL2 (a known anti-apoptotic protein determined to be involved with neuroblastoma drug resistance) has been demonstrated as a direct target of miR-497 in neuroblastoma cells, further highlighting an important tumor suppressor role of this miRNA in this cancer." (PMID 23531080, 2013). "Moreover, BH3 peptidomimetics that antagonize antiapoptotic Bcl-2 proteins showed antitumor activity as single agents against neuroblastoma." (PMID 23420072, 2013). "Interestingly, high expression levels of Bcl-2 or Mcl-1 correlated with advanced disease in neuroblastoma." (PMID 23420072, 2013). "To test whether DIABLO can be functionally activated upon an apoptotic stimulus, we treated neuroblastoma cells with the BCL2 inhibitor ABT263, which results in stimulation of pore formation in the mitochondria." (PMID 22788920, 2012). "BCL2 has been reported to be targeted by the same miRNA in neuroblastoma cells." (PMID 22829753, 2012). "This hypothesis is based on the evidence that exogenous ET-1 significantly increased BCL-2 protein levels in neuroblastoma cells and this effect was attenuated in the presence of ETA/B receptor antagonists." (PMID 22134829, 2012). "In addition, BCL2 mRNA was recently identified as a true miR-34a target in neuroblastoma cell lines." (PMID 20433755, 2010). "In addition to stimulating angiogenesis in tumour growth, VEGF also mediates neuroprotection promoting neuroblastoma cellular survival by increasing Bcl-2 and pro-caspase 3 expressions." (PMID 19895696, 2009). "Bcl-2 overexpression inhibited TRAIL-induced Bax activation, loss of MOMP, and cleavage of caspase-8 into p43/p41 and p18 active fragments, cleavage of Bid, and processing of the caspase-3 p20 fragment into the p17/p12 active fragments in SH-EP neuroblastoma cells." (PMID 37065863, 2023). "Therefore, targeting these spliceosomal components could be of interest in re-sensitizing MCL1-dependent neuroblastoma cells to Bcl-2 inhibitors." (PMID 34065983, 2021). "In addition, promising results were reported in high-risk neuroblastoma treated with the combination of both GSK-J4 and venetoclax (bcl-2 inhibitor).However, we also know little about the cooperation therapeutic effect of GSK-J4 and venetoclax in AML especially in primary refractory/relapsed AML." (PMID 32514253, 2020). "Inhibitors of PLK1, such as BI6727 and BI2356, preferentially trigger apoptosis of MYCN-amplified neuroblastoma and small cell lung cancer, and this therapeutic efficacy is synergistically enhanced by combined use with antagonists of anti-apoptotic B cell lymphoma 2 (BCL2)." (PMID 33614505, 2020). "Moreover, BCL-2 overexpression is reported to be an important mechanism by which apoptosis and drug resistance is altered in retinoic acid (RA)-induced differentiation of neuroblastoma cells." (PMID 31652776, 2019).
neuroblastoma (continued). "Therefore, combined inhibition of Bcl-2/Mcl-1 e.g. by TW-37 in N-Myc amplified neuroblastoma may represent an interesting therapeutic strategy." (PMID 30885150, 2019). "Therefore, combined inhibition of Bcl-2/Mcl-1 by TW-37 in N-Myc amplified neuroblastoma may represent an interesting therapeutic strategy." (PMID 30885150, 2019). "Hence, combinatorial strategies of inducing differentiation in poorly differentiated neuroblastoma cells with RA, followed by pharmacologically altering BCL-2 expression could be useful to sensitize neuroblastoma to apoptosis." (PMID 31652776, 2019). "Indeed, in a large subset of neuroblastoma patients, an elevated level of Bcl-2 has been detected." (PMID 29686263, 2018). "Mouse neuroblastoma N2a cells cotransfected with Swedish mutant APP and Δ9 deleted presenilin-1 (N2a/Swe.Δ9) recapitulated similar loss of mitochondrial integrity and function and evidenced increased mitochondrial apoptotic pathway, with a higher Bax/Bcl2 ratio and augmented caspase-3 activity." (PMID 26064418, 2015). "Also, the anti-apoptotic mitochondrial BCL2 protein is highly expressed in neuroblastoma." (PMID 22788920, 2012). "Oleacein induces apoptosis in neuroblastoma cells via upregulating BAX and downregulating BCL-2 protein expression." (PMID 39203892, 2024). "In cisplatin-resistant neuroblastoma, however, MCL1 was by far the most promising anti-apoptotic target, with sensitivity to BCL2 and BCL-XL inhibitors lost upon chemoresistance." (PMID 37723317, 2023). "Mechanistically, neuroblastoma cell lines identified as BCL-2 dependent possess high levels of BCL-2 and BIM:BCL-2 complexes, and ABT-199 mediates its effects by displacing BIM from BCL-2, allowing mitochondrial apoptosis to proceed." (PMID 35568716, 2022). "In vitro, MCL-1 inhibition sensitised neuroblastoma cells to ABT-199 treatment, highlighting the protective role MCL-1 mediates in cells with high BCL-2:BIM complex levels." (PMID 35568716, 2022). "Chemotherapy resistance of neuroblastomas with amplified MYCN was related with Cat D expression, and they suggest that enhancement of Bcl-2 anti-apoptotic function." (PMID 35715412, 2022). "Since induction of neural differentiation markers BCL2 and NTRK2 was suppressed, we compared the expression of VIM, a characteristic marker of S-type neuroblastoma cells, in untreated wild-type and TOP2B null SH-SY5Y cells." (PMID 35831557, 2022). "Our study presents evidence for the effects of MSCs on SH-SY5Y neuroblastoma cells by investigating Annexin-V and Caspase-3 assay, telomere length, telomerase, and β-Galactosidase activity assessment through BAX and BCL2 signaling pathways." (PMID 35317118, 2021). "To evaluate the role of the different antiapoptotic BCL-2 proteins and investigate the potential of BH3-mimetics in neuroblastoma, we directly compared the efficacy of ABT-199, S63845 and A1331852 in neuroblastoma cell lines." (PMID 32203216, 2020). "By using selective BH3-mimetics, this study demonstrates that BCL-2, BCL-XL, and MCL-1 are all relevant therapeutic targets in neuroblastoma." (PMID 32203216, 2020). "Taken together, these data highlight that BCL-XL, BCL-2 and MCL-1 all possess essential antiapoptotic functions in neuroblastoma." (PMID 32203216, 2020). "The expression of Bcl-2, one of the anti-apoptotic proteins, was dramatically decreased in METH-treated SH-SY5y neuroblastoma cells but was rescued in lupenone pre-treated cells." (PMID 32120831, 2020). "Bioinformatics analysis using starBase showed, among 8 potential targets which were expressed in neuroblastoma, that CDC42 and BCL2 mRNA levels were up-regulated most in SK-N-SH cells." (PMID 31889909, 2019).
neuroblastoma (continued). "Stress preconditioned neuroblastoma SH-SY5Y cells had escalated the synthesis of reduced Trx, active TrxR, and Bcl-2, a pro-apoptosis protein." (PMID 31547465, 2019). "It is known that high levels of NOXA expression can confer sensitivity to BCL2 inhibitors and is a likely explanation for the sensitivity of MYC- amplified neuroblastoma cell lines to these agents." (PMID 30326621, 2018). "BCL2 and MCL1 expression levels are correlated with the efficacy of BCL2 antagonists in neuroblastoma cells." (PMID 28915653, 2017). "BCL2 is an anti-apoptotic member of the BH3 family and is highly expressed in the majority of neuroblastoma tumors." (PMID 28915653, 2017). "BIM displacement from BCL-2 to MCL-1 also occurred in vivo, confirming the pivotal role of MCL-1 in the biological mechanism by which neuroblastoma cells can escape from ABT199-induced apoptosis." (PMID 27056887, 2016). "High BCL-2-expressing neuroblastoma cell lines CHP126, KCNR and SJNB12 and low BCL-2-expressing cell lines SKNAS and SHEP2 were treated with increasing doses of ABT199 to study effects on apoptosis." (PMID 27056887, 2016). "In our therapeutic approach, ABT-199 eliminates this pro-survival BCL-2 signal, thus allowing for MYCN-mediated pro-apoptotic signaling to help push the neuroblastoma cells toward the apoptotic threshold." (PMID 26859456, 2016). "The water extract of Panax ginseng also inhibited apoptosis MPP(+)-induced in the human neuroblastoma SH-SY5Y cells by decreasing Bax levels, caspase-3 activity, and cytochrome release and increasing Bcl2 levels." (PMID 26064418, 2015). "Using cultured rat PC12 cells or rat B104 neuroblastoma cells, other groups found upregulation in anti-apoptotic genes, BCLXL and BCL2, respectively." (PMID 25324845, 2014). "Recently, we demonstrated that miR-204 increases sensitivity of neuroblastoma cells to CDDP, in part, through the down-regulation of BCL2." (PMID 23531080, 2013). "In vitro profiling of neuroblastoma cells using BH3-domain peptides revealed that, in addition to Mcl-1, also other antiapoptotic Bcl-2 proteins can confer resistance to chemotherapy." (PMID 23420072, 2013). "Oral administration of I-BET726 to mouse xenograft models of human neuroblastoma results in tumor growth inhibition and down-regulation MYCN and BCL2 expression, suggesting a potential role for these genes in tumor growth." (PMID 24009722, 2013). "Co-expression of BCL2 and MYCN in neuroblastoma cell lines increases tumorigenicity and protects cells from apoptosis." (PMID 24009722, 2013). "Neuroblastoma cells utilize VEGF both as a stimulator of angiogenesis and an inhibitor of apoptosis through upregulation of Bcl-2 expression." (PMID 21876694, 2012). "N-Myc and Bcl-2 co-expression induces MMP-2 secretion and activation leading to tumorigenic phenotype in human neuroblastoma cells." (PMID 21876694, 2012). "We investigated the effects of TIR on markers of neuronal growth (CREB and BDNF), apoptosis (BAX/Bcl2 ratio) differentiation (pAkt, MAP2, GAP43, and AGBL4), and insulin resistance (GLUT1, GLUT4, GLUT3 and SORBS1) in a neuroblastoma cell line (SHSY5Y) exposed to normal and high glucose concentration." (PMID 38287296, 2024). "It was also found that in trophically stressed neuroblastoma cells, overexpression of MYCN could weaken the anti-apoptotic effect of Bcl-2 and increase the cell death." (PMID 37543638, 2023). "Furthermore, APZ exhibited its neuroprotective properties in SH-SY5Y human neuroblastoma cells by increasing both BDNF and Bcl-2 levels." (PMID 38256307, 2023). "Interestingly, individual studies in SCLC or neuroblastoma have also reported many of these associations, such as MEK inhibitors for neuroblastoma, HSP90 inhibitors for SCLC and neuroblastoma, and BCL2 inhibitors for SCLC and neuroblastoma." (PMID 37255415, 2023).